TET1 (tet methylcytosine dioxygenase 1)
Diseases named in the same sentence as TET1 in open-access papers (continued):
Sharing a sentence is not in itself a finding about the gene and the disease.
B-cell lymphoma (13 papers, 2015 to 2025). "As a result, Tet1 KO mice were predisposed to increased self-renewal, DNA damage accumulation, and lymphoid skewing, eventually developing B-cell lymphoma after a long latency." (PMID 36675240, 2023). "The mutation or downregulation of TET1 is frequently found in patients with non-Hodgkin B-cell lymphoma, including DLBCL and follicular lymphoma." (PMID 36203205, 2022). "In mouse genetic studies, Tet1-deficient B cell progenitors developed B cells lymphomas; in analogous human studies, the Tet1 promoter was found to be hypermethylated with concomitant reduction in Tet1 expression in patients with non-Hodgkin lymphoma." (PMID 29535729, 2018). "In additional studies, mice with a combined Tet2- and Tet3-deficiency in developing B cells developed B cell lymphoma and succumbed to disease within 5–6 months of age, much earlier than the 15–20 months observed in Tet1/Tet2-deficient mice." (PMID 29535729, 2018). "Tet1-deficient mouse B cell progenitors showed increased self-renewal in vitro and the mice developed B cell lymphomas at an advanced age (18–24 months)." (PMID 28408905, 2017). "Intriguingly, whereas Tet2-deficient mice develop myeloid leukemia, dual Tet1/Tet2 deficiency resulted instead in the development of B cell lymphoma with delayed disease progression (12–15 months) compared to Tet2 deficiency alone." (PMID 28408905, 2017). "A large body of studies evidenced the key role of TET2 in most tumors and TET1 mutation was also suggested as tumor suppressor in B-cell lymphoma." (PMID 27183914, 2016). "Gene sequencing showed that the mutation dominant in TET1-deleted mice was observed in non-Hodgkin B cell lymphoma (B-NHL)." (PMID 27183914, 2016). "Tet1-deficient mice and Tet1/Tet2 double knockout mice develop B cell lymphoma." (PMID 35805009, 2022). "In our own studies, mice with combined early deletion of Tet2 and Tet3 in developing B cells using Mb1-Cre developed progressive B cell lymphoma and succumbed to disease within 5–6 months of age, an earlier onset compared to 15–20 months observed in Tet1/2-deficient mice." (PMID 28408905, 2017). "The loss of TET1 function predisposes HSCs to malignancy and, more specifically, B-cell lymphoma." (PMID 28294974, 2017). "Then, they reasoned that based on these data, TET1-deficient B cell lymphomas might have specific mutations." (PMID 26146524, 2015). "Consistent with these mouse genetic studies, the TET1 promoter was shown to be hypermethylated and TET1 expression was repressed in human patients with non-Hodgkin B cell lymphoma." (PMID 28408905, 2017). "TET1-deficient tumors reveal mutations of non-Hodgkin B cell lymphoma (B-NHL), showing that TET1 is required for B cell lineage." (PMID 26861406, 2016). "In mice, they found that deletion of TET1 promoted the development of B cell non-Hodgkin lymphoma (B-NHL)." (PMID 26146524, 2015). "In addition to inactivating mutations, TET1 downregulation is commonly detected in B-cell malignancies including B-ALL, B-cell lymphoma, and MM." (PMID 36203205, 2022). "Moreover, hypermethylation and thus transcriptional silencing of TET1 is also observed in B-cell lymphoma, where its tumor suppressor activity was demonstrated in vivo, as KO of TET1 resulted in decreased survival of the mice." (PMID 36059621, 2022). "Lately, a study demonstrated that TET1 deletion was able to induce B-cell lymphoma." (PMID 27183914, 2016). "Somatic alteration of TET2, TET1/TET2 deficiency (TET1/2 double knockout), and TET2/TET3 disruption (TET2/3 double knockout) can lead to a wide range of myeloid and lymphoid malignancies, late-onset B-cell lymphoma, and rapid and fully penetrant myeloid leukemia." (PMID 35429301, 2022). "In non-Hodgkin’s B cell lymphomas, such as DLBCL or follicular lymphoma (FL), TET1 was epigenetically silenced through promoter hypermethylation." (PMID 36675240, 2023).
glioblastoma (13 papers, 2012 to 2025). The most malignant astrocytic tumor (WHO grade IV). "It has been shown that TET1/2/3 expression is downregulated in glioblastoma and that TET3 levels are associated with a better prognosis in patients with glioblastoma." (PMID 40599235, 2025). "Similar consequences were observed by former investigations that low levels of TET1 were associated with reduced survival in glioblastoma." (PMID 35965532, 2022). "Forloni et al56 investigated this topic, demonstrating that oncogenic EGFR silenced tumor suppressor genes in lung adenocarcinomas and glioblastomas by inhibiting TET1 through C/EBPα." (PMID 40520993, 2025). "Its knockdown inhibited glioblastoma progression resulting in longer survival of mice, but with TET1 becoming overexpressed again, the tumorigenicity was restored." (PMID 31311166, 2019). "In contrast to other cancers, 5hmC levels in proneural subtype of glioblastoma were found to be increased, most likely due to high expression and activity of TET1 enzyme." (PMID 31311166, 2019). "In proneural glioblastomas, TET1-catalytic production of 5hmC is required for increased tumorigenicity." (PMID 27557497, 2016). "In addition, oncogenic EGFR induces the silencing of tumor suppressor genes by inhibiting TET1 and promoting glioblastoma development." (PMID 40599235, 2025). "Low levels of TET1 and TET3 were also associated with reduced survival in glioblastoma." (PMID 22829908, 2012). "Hypoxia‐inducible factor‐1 (HIF‐1) is essential for glioblastoma development; hypoxia leads to the upregulation of HIF‐1, which promotes the transcriptional activation of TET1 and the induction of hypoxia‐responsive genes." (PMID 40599235, 2025).
neuroblastoma (12 papers, 2016 to 2025). Neuroblastoma (NB) is the most common solid, extracranial childhood tumor. "The recessive model of TET1 rs3998860 showed significantly increased risk of neuroblastoma in all clinical staging subgroups." (PMID 37347215, 2023). "In summary, our study demonstrates that TET1 gene rs3998860 G > A and rs12781492 A > C significantly increase neuroblastoma risk." (PMID 37347215, 2023). "Based on the impact of TET1 rs3998860 G > A and rs12781492 A > C on susceptibility to neuroblastoma, we further explored the impact of these two loci on expression of nearby genes." (PMID 37347215, 2023). "The results for the recessive model (AA vs. GG/GA) of TET1 rs3998860 showed significantly increased neuroblastoma risk in subgroups >18 months of age and males." (PMID 37347215, 2023). "Stratification analysis for the association between TET1 risk genotypes with neuroblastoma susceptibility in Jiangsu children." (PMID 37347215, 2023). "Considering the effect of confounding factors, we further explored the association between TET1 rs3998860 and susceptibility to neuroblastoma through stratification analysis." (PMID 37347215, 2023). "We further analysed the impact of TET1 gene polymorphisms on susceptibility to neuroblastoma by stratified analysis of age, sex, site of origin and clinical stage." (PMID 37347215, 2023). "Multivariate logistic regression analysis was used to evaluate the association between TET1 gene polymorphisms and susceptibility to neuroblastoma." (PMID 37347215, 2023). "The results showed that only the GG genotype of TET1 rs3998860 significantly increased neuroblastoma risk compared to the AA genotype." (PMID 37347215, 2023). "Our study is the first to clarify the association between TET1 gene polymorphisms and susceptibility to neuroblastoma in children in Jiangsu, China, and its possible mechanism." (PMID 37347215, 2023). "Our results suggest that TET1 gene polymorphisms (rs3998860 G > A and rs12781492 A > C) are associated with increased neuroblastoma risk." (PMID 37347215, 2023). "We used a case–control study to explore the association between risk of neuroblastoma and TET1 gene polymorphisms in children in Jiangsu, China." (PMID 37347215, 2023). "Three TET1 gene polymorphisms (rs16925541 A > G, rs3998860 G > A and rs12781492 A > C) in 402 Chinese patients with neuroblastoma and 473 cancer‐free controls were assessed using TaqMan." (PMID 37347215, 2023). "For this, we analyzedby confocal microscopy the cellular association, of Tet1-CsiRNA-Cy5PStail functionalized structures with a neuronal cell lineND7/23 (neuroblastoma cell type) known to express the neuronal trisialogangliosidecell receptor Gt1b28." (PMID 36519952, 2022). "Likewise, TET1–3 polymorphisms are associated with neuroblastoma risk by maintaining stemness and cellular plasticity through non‐catalytic mechanisms." (PMID 40984038, 2025). "The potential mechanisms of TET1 gene polymorphisms in neuroblastoma need to be further elucidated." (PMID 37347215, 2023). "Based on the importance of the TET1 gene in neuroblastoma, we hypothesize that TET1 gene polymorphisms have an impact on risk of neuroblastoma." (PMID 37347215, 2023). "In summary, TET1 gene polymorphisms are significantly associated with increased neuroblastoma risk; further research is required for the potential mechanism and therapeutic prospects in neuroblastoma." (PMID 37347215, 2023). "TET1 rs3998860 and rs12781492 may increase neuroblastoma risk by influencing mRNA expression of CCAR1." (PMID 37347215, 2023). "Therefore, we explored the impact of TET1 gene polymorphisms on risk of neuroblastoma through a case–control study." (PMID 37347215, 2023). "To test our hypothesis, we conducted a case–control study in Jiangsu, China, to explore whether TET1 gene polymorphisms are associated with susceptibility to neuroblastoma." (PMID 37347215, 2023). "Association of TET1 gene polymorphisms with neuroblastoma risk in children from Jiangsu province." (PMID 37347215, 2023).
neuroblastoma (continued). "However, the important role of TET1 gene mutations in neuroblastoma needs to be further explored." (PMID 37347215, 2023). "A member of the TET (ten‐eleven translocation) family, TET1 (tet methylcytosine dioxygenase 1) has been shown to play an important biological role in cancer, including neuroblastoma, in recent years." (PMID 37347215, 2023). "Reduced oxygen conditions (1% O2) upregulated TET1, increased global 5hmC, and increased 5hmC level at hypoxia response genes in neuroblastoma cells." (PMID 33925659, 2021). "In neuroblastoma cells, hypoxia lead to TET1 upregulation, and TET1 is required for full induction of hypoxia-responsive genes and global 5hmC level increases." (PMID 27557497, 2016). "Currently, there is no research indicating that TET1 gene polymorphisms are associated with susceptibility to neuroblastoma." (PMID 37347215, 2023). "Finally, the specific mechanism of TET1 rs3998860 and rs12781492 in neuroblastoma remains to be elucidated." (PMID 37347215, 2023). "Furthermore, in a previous report, it was suggested that hypoxia leads to transcriptional activation of TET1, which facilitated hypoxic gene induction in neuroblastoma, showing the important role of TET1 in neuroblastoma development." (PMID 27113584, 2016). "Specifically, polymorphisms such as rs3998860 G>A and rs12781492 A>C in the TET1 gene, rs10007915 G>C and rs7670522 A>C in the TET2 gene, rs828867 G>A in the TET3 gene, and rs13181449 C>T in the NSUN2 gene have been identified as closely linked to neuroblastoma susceptibility." (PMID 40984038, 2025). "However, the association between TET1 gene polymorphisms and susceptibility to neuroblastoma has not been reported." (PMID 37347215, 2023). "However, the important role of TET1 gene polymorphisms in cancer, including neuroblastoma, has not been revealed." (PMID 37347215, 2023). "The results further indicated TET1 might serve as a promising therapeutic target in neuroblastoma." (PMID 27113584, 2016).
triple-negative breast carcinoma (12 papers, 2019 to 2025). An invasive breast carcinoma which is negative for expression of estrogen receptor (ER), progesterone receptor (PR), and human epidermal growth factor receptor 2 (HER2). "Though reduction of TET1 expression in most tumors was once considered a hallmark of cancer, recent studies have shown that high TET1 expression was associated with tumor grade and poor outcome in triple-negative breast cancer (TNBC)." (PMID 37430206, 2023). "TET1 is also overexpressed in 40% of patients with triple-negative breast cancer, where it is associated with DNA hypomethylation and activation of oncogenic pathways, leading to poor overall survival." (PMID 31266538, 2019). "After TET1 deletion in triple-negative breast cancer cell models, decreased expression of PI3K pathway genes, up-regulation of immune response genes, and reduced cell proliferation were observed." (PMID 40520993, 2025). "A study based on The Cancer Genome Atlas (TCGA) datasets revealed that almost 40% of patients with triple-negative breast cancer displayed overexpression of TET1." (PMID 39201247, 2024). "In another study, we observed in triple negative breast cancer that TET1 is repressed by polycomb repressive complex 2 (PRC2)-mediated H3K27me3 silencing." (PMID 35805009, 2022). "In triple-negative breast cancer, which is one of the most hypomethylated cancers, TET1-mediated hypomethylation activates oncogenic signaling." (PMID 34844636, 2021). "In triple negative breast cancer (TNBC), EZH2 was shown to downregulate TET1 expression and consequently inhibited tumor senesence and apoptosis, indicating that TET1 is a tumor suppressor, also in TNBC." (PMID 35646706, 2022). "Similarly, TET1, an epigenetic modulator overexpressed in CAFs, reshapes the CAF epigenome by hypomethylating oncogenic pathways (e.g., PI3K, EGFR, PDGF) in triple-negative breast cancer." (PMID 40216762, 2025).
cholangiocarcinoma (11 papers, 2019 to 2025). A carcinoma that arises from the intrahepatic biliary tree (intrahepatic cholangiocarcinoma) or from the junction, or adjacent to the junction, of the right and left hepatic ducts (hilar cholangiocarcinoma). "Here it is found that TET1 is highly expressed in cholangiocarcinoma (CCA) and is associated with a poor prognosis." (PMID 39477806, 2024). "Experiments using OG-related compounds revealed that TET1 promoted cholangiocarcinoma cell malignancy by increasing 5hmC levels." (PMID 40520993, 2025). "Mechanistically, TET1 enhances cell proliferation and inhibits apoptosis in cholangiocarcinoma through epigenetic regulation of the Notch and EGFR signaling pathways." (PMID 40599235, 2025). "Inhibiting TET1 activity through various methods suppressed cholangiocarcinoma development by affecting cell growth and apoptosis." (PMID 40520993, 2025). "Subsequently, we investigated the impact of phosphatase inhibitors and TET1 inhibitors on the progression of the in situ cholangiocarcinoma model." (PMID 39477806, 2024). "The findings demonstrated that TET1 enhanced cholangiocarcinoma EMT, with this effect dependent on its catalytic activity." (PMID 39477806, 2024). "Two phosphatase inhibitors, staurosporine and AZD0156, inhibit epithelial‐to‐mesenchymal transition (EMT) in cholangiocarcinoma cells by suppressing TET1 expression." (PMID 39477806, 2024). "Ten–eleven translocation protein 1 (TET1) exerts its pro‐carcinogenic effect in cholangiocarcinoma by catalyzing the demethylation of the claudin‐3 (CLDN3) promoter region." (PMID 39477806, 2024). "Subsequently, in vivo and in vitro experiments showed that TET1 promotes cholangiocarcinoma proliferation, invasion, and metastasis." (PMID 39477806, 2024). "The progression of cholangiocarcinoma is highly correlated with TET1 expression." (PMID 40599235, 2025). "In addition, two phosphorylation inhibitors, staurosporine and AZD0156, inhibit cholangiocarcinoma progression by destabilizing the protein by inhibiting TET1 phosphorylation." (PMID 39477806, 2024). "TET1 has also been shown to be an oncogenic driver in IDH‐wild‐type cholangiocarcinoma." (PMID 36618446, 2021). "The progression of cholangiocarcinoma (CCA) was highly correlated with TET1." (PMID 34656178, 2021). "Increasing evidence revealed that ten‐eleven translocation 1 (TET1) plays an important role in tumorigenesis and chemoresistance, but its functions in gemcitabine resistance in cholangiocarcinoma (CCA) remain unknown." (PMID 30784212, 2019). "The in situ cholangiocarcinoma model mice were constructed in C57BL/6 mice and tet1‐CKO mice, which demonstrated prolonged survival and an improved prognosis in TET1 knockout mice." (PMID 39477806, 2024). "TET1 showed both very low expression in normal tissue and significant upregulation in tumor only in HCC and Cholangiocarcinoma (CHOL)." (PMID 38967794, 2024). "Finally, the abundance of IDH1/2 mutations in gliomas and cholangiocarcinomas, but lack of TET2 mutations, are likely a reflection of TET enzymes functioning in tissue specific patterns—TET1, for example, has very recently been shown to be an oncogenic driver in IDH‐wt cholangiocarcinoma." (PMID 36618446, 2021).